LOX (lysyl oxidase)
Diseases named in the same sentence as LOX in open-access papers (continued):
Sharing a sentence is not in itself a finding about the gene and the disease.
tumor (continued). "Moreover, elevated LOX activity found on invasive edges of tumours has been noted to drive actin polymerization, cell contractility, and migration, providing a pathway for successive tumour cells to follow." (PMID 30287763, 2018). "After having verified that lysyl oxidase activity depending on the tumor can affect proliferation and tumor growth in both ways, either negatively or positively, we now examined how these oppositional effects could be explained." (PMID 29780168, 2018). "We hypothesized that lysyl oxidase activity could affect tumor growth in two converse ways: on one hand, it has been shown that increased tissue rigidity, e.g., as a consequence of lysyl oxidase activity, can increase tumor cell proliferation." (PMID 29780168, 2018). "Furthermore, ECM cross-linkers such as transglutaminase and lysyl oxidase (LOX) present within TME participate in tumor ECM modifications by cross-linking the newly generated collagen fibers and other ECM proteins." (PMID 30220913, 2018). "Thus, LOX function appears context-dependent, exhibiting both tumor promoting and suppressing properties in PCa." (PMID 29732010, 2018). "Overexpressed LOX in cancers is related to tumorigenesis, tumor progression and metastasis." (PMID 29728125, 2018). "However, LOX was initially described as a tumor suppressor, by inhibiting HRAS-mediated oncogenic transformation." (PMID 29732010, 2018). "On the contrary, another group found that high LOX expression in adjacent non-malignant prostate epithelium was associated with shorter cancer-specific survival, and LOX overexpression in tumor epithelium was related to higher Gleason score and metastasis." (PMID 29732010, 2018). "The function of LOX as a tumor suppressor versus promoter may thus depend, besides its processing and activity, on the cell type, stage of progression, cellular contexts, and the mode of cell migration/invasion." (PMID 30701028, 2018). "Tumour-derived LOX expression is driven by HIF1-α within hypoxic regions in tumours." (PMID 29098360, 2018). "Overexpression of LOX/LOXL2 increased tumor establishment and initial growth of the 4T1 tumors." (PMID 29780168, 2018). "However, it has also been reported that lysyl oxidase activity and collagen cross-linking has a strong effect on tumor angiogenesis." (PMID 29780168, 2018). "Our data show that changing nuclear LOX expression at the primary tumour may be a marker of transition to metastasis." (PMID 28947950, 2017). "Altogether, we suggest the possibility that a HIF-1α/LOX regulatory mechanism may act in synergy to foster tumor formation along with the adaptation of tumor cells to hypoxia." (PMID 28143503, 2017). "This allows us to use primary tumour LOX expression and localisation as a robust prognostic indicator for patients at high risk of relapse independent of whether they received preoperative RT." (PMID 28947950, 2017). "In contrast, when analysing nuclear immunostaining patterns, the frequency of high LOX expression was significantly lower in primary tumour (14% of 77, and 13% of 60) than in normal mucosa (47% of 62, and 70% of 54) in both non-RT and RT groups (P < 0.001 for both)." (PMID 28947950, 2017). "Thus, we show that LOX regulates EGFR cell surface retention to drive tumour progression, and we validate the therapeutic potential of inhibiting this pathway with the small molecule inhibitor CCT365623." (PMID 28416796, 2017). "Lysyl oxidase (LOX) catalyzes the formation of lysine-derived cross-links in collagen and elastin and it is involved in several other biological functions (e.g. development, tumor suppression, cell motility and cellular senescence)." (PMID 28719655, 2017). "LOX-induced collagen cross-linking resulted in stiffening of the matrix around tumor cells." (PMID 28423580, 2017). "Moreover, our latest results show that a high expression of LOX in primary tumour cells leads to tumour-driven pre-metastatic bone lesions whereas inhibition of LOX abrogates this process." (PMID 28947950, 2017).
tumor (continued). "Lysyl oxidase (LOX) remodels the tumour microenvironment by cross-linking the extracellular matrix." (PMID 28416796, 2017). "Importantly though, despite implicating overall LOX expression, neither of these papers profiled the specific cellular localisation of LOX in tumour tissues, making this the first report to do so." (PMID 28947950, 2017). "Moreover, hypoxia has been shown to be a microenvironmental factor in many diseases and induces tumor expression of LOX through HIF-1α to enhance cell–matrix adhesion, migration, invasion, and metastasis." (PMID 28036074, 2016). "The reasons behind these seemingly contradictory results are unknown, but they show that the role of LOX catalytic activity during tumour progression is complex." (PMID 26804196, 2016). "Conversely, at later time points inhibiting LOX may affect other aspects of LOX than collagen cross-linking, that possibly could enhance tumour growth." (PMID 26804196, 2016). "However, MNU treatment downregulated LOXs in the course of tumor development suggesting that LOX exhibit antitumorigenic rather protumorigenic effects." (PMID 27473871, 2016). "Further studies are needed to determine whether the different LOX enzymes have different functions in tumours or if they are able to compensate for each other." (PMID 26804196, 2016). "In addition, hypoxia also induces stromal expression of LOX, which causes collagen linearization, increases ECM stiffness, and induces epithelial phenotype loss in cancer cells, thus enhancing tumor cell invasion through ECM remodeling." (PMID 28036074, 2016). "Alternatively, in tumours with low collagen content, other tumour suppressing functions of LOX may be dominating." (PMID 26804196, 2016). "The finding that LOX-dependent crosslinking of human fibroblast-derived ECM is required to promote tumor cell migration, indicates that anti-Endo180 and/or anti-LOX therapy is a feasible therapeutic option for the treatment of visceral tumors surrounded by a stiffened stroma." (PMID 26567111, 2016). "Correspondingly, LOX is described to act as tumor suppressor or promoter of tumor progression." (PMID 27336447, 2016). "As a component of the extracellular matrix that enhances cell motility and migration, LOX could play a key role in tumor development and progression." (PMID 26882568, 2016). "Inhibition of this defence in situations where the tumour-promoting role of LOX within the tumour is of limited importance may therefore actually speed tumour growth." (PMID 26804196, 2016). "Indeed, immunostaining revealed a strong induction of LOX expression in tumor xenografts produced by cells over expressing Hpa2." (PMID 26968815, 2016). "This suggests that LOX was more active in small tumours that contained more collagen, and inhibiting LOX using BAPN at this time point may therefore suppress tumour growth." (PMID 26804196, 2016). "In contrast, a few reports have also indicated the tumor-suppressing role of LOX." (PMID 28036074, 2016). "LOX reportedly modifies the tumor microenvironment to enhance cancer invasion and metastasis." (PMID 26882568, 2016). "However, LOX has also been shown to have tumor suppressor function, and the more recent studies have shown that the tumor suppressor function is due to LOX-PP." (PMID 28036074, 2016). "In patients we have noted that high LOX in tumour epithelial cells was associated with high Gleason score but not with survival, whereas high LOX in non-malignant prostate epithelial cells was associated with a poor outcome." (PMID 26804196, 2016). "We aimed to target the molecules whose functions depend on the transition metals in the tumor microenvironment, such as matrix metalloproteinases, lysyl oxidase, and vascular endothelial growth factor, which can be used as drug targets to inhibit tumor growth or metastasis." (PMID 27556432, 2016). "Together with our results, this indicates that LOX inhibition could be effective in preventing tumour initiation and metastatic colonization." (PMID 26804196, 2016).
tumor (continued). "Interestingly, when full-length LOX, including LOX enzyme and LOX-PP activities was expressed in A673 cells, the anti-tumor effects prevailed." (PMID 26258070, 2015). "Furthermore, lysyl oxidase secreted from hypoxic tumor cells mediates the formation of premetastatic niche, accumulates at premetastatic site, and provides crosslinking of type IV collagen in the basement membrane, resulting in recruitments for myeloid cells." (PMID 27441234, 2015). "LOX is a secreted amine oxidase that plays a key role in modifying the primary tumor microenvironment by crosslinking collagens and elastin in the ECM thereby causing stiffening of the matrix and enhancing the invasive and metastatic properties of the tumor." (PMID 25790191, 2015). "We only could detect a significant dependency of drug diffusion from lysyl oxidase expression in tumor spheroids at a reduced oxygen level of 2%." (PMID 26620400, 2015). "Therefore, we treated mice with a palpable tumor burden with the LOX-blocking antibody alone and in combination with gemcitabine." (PMID 26077591, 2015). "In contrast, some loci have been found hypermethylated with age (e.g., estrogen receptor, interferon γ, insulin-like growth factor II, promoters of tumor-suppressor genes such as lysyl oxidase (LOX), p16INK4a, runt-related transcription factor 3 (RUNX3), and TPA-inducible gene 1 (TIG1))." (PMID 26703582, 2015). "Using mouse and human colorectal tumor models as well as genetic and pharmacologic inhibition of LOX activity, we determined that the effect of inhibition of LOX activity on colorectal tumorigenesis depends on LOX-derived metabolites in both the tumor cells and the host stroma." (PMID 25576922, 2015). "Thus, in this environment, expression of LOX protein should have a marked impact on the surrounding stroma, driving the cross-linking of collagen and elastin in the tumor microenvironment." (PMID 26077591, 2015). "The easiest strategy is to evaluate the effect of the administration of LOX-PP on tumor cells." (PMID 26258070, 2015). "LOX expression was verified by Western blot analysis on tumor homogenates and cell lines." (PMID 26265048, 2015). "However, LOX score in tumor stroma and TINT stroma appeared unrelated to these tumor characteristics (data not shown)." (PMID 26501565, 2015). "LOX inhibits HRAS-induced tumor formation and reverse HRAS-transformation of fibroblasts." (PMID 26501565, 2015). "LOX protein expression in the radical prostatectomies was similar to the staining in the in the TMAs showing variable staining intensity in both normal and tumor epithelial and stromal cells." (PMID 26501565, 2015). "Cells in culture may be subjected to similar stresses as metastasizing tumor cells, and in this situation, cell matrix proteins such as LOX could support cell survival and proliferation." (PMID 26077591, 2015). "This suggests that a specific interaction of [18F]FB-GGGDPKGGGGG-NH2 with LOX in the tumor tissue may occur, but only at the beginning of the dynamic observation." (PMID 26265048, 2015). "Furthermore, based on the detection of LOX in the serum of mice bearing irradiated tumor xenografts, future studies should also investigate LOX levels in human patients undergoing radiotherapy treatment." (PMID 25052686, 2014). "Interestingly, LOX has a dual role in cancer both as a tumour suppressor and as a metastasis promoter." (PMID 25141126, 2014). "Our study demonstrates that increased expression of LOX is correlated with an advanced stage of GC and that it may contribute to tumor development." (PMID 25060181, 2014). "To determine a functional role of IR-induced LOX secretion, we analyzed the invasive capacity of naïve A549 cells, stimulated with conditioned media derived from sham- or irradiated control and anti-LOX siRNA-targeted A549 tumor cells." (PMID 25052686, 2014).
tumor (continued). "In vivo studies for confirming IR-enhanced LOX were performed employing immunohistochemistry of tumor tissues and ex vivo analysis of murine blood serum derived from locally irradiated A549-derived tumor xenografts." (PMID 25052686, 2014). "TGF-β1 regulates LOX activity in osteoblastic cells on the pre-and posttranslational level, so IR-induced TGF-β1 could play a role in promoting LOX secretion from our tumor cells." (PMID 25052686, 2014). "Our studies demonstrated an increase of LOX secretion in irradiated tumor cell lines in vitro." (PMID 25052686, 2014). "Elevated LOX levels could be identified in response to irradiation in conditioned media derived from established tumor cells from multiple different tumor entities and to different magnitudes." (PMID 25052686, 2014). "In addition, LOX expression was determined in the lymph node metastases of 17 patients, and was found to be significantly lower than in the matched primary tumours of the same patients." (PMID 25141126, 2014). "LOX was secreted in a dose dependent way from several tumor cell lines in response to irradiation." (PMID 25052686, 2014). "In this study, we investigate the effects of IR on LOX secretion by tumor cells to determine a putative role in an IR-induced stress response, which might promote treatment resistance." (PMID 25052686, 2014). "These LOX expression patterns may seem inconsistent, and may reflect the dual role of LOX in tumour suppression and metastatic progression." (PMID 25141126, 2014). "Furthermore, LOX promotes tumor growth and progression in vivo, cancer cell invasion, and premetastatic niche formation to foster distant metastases." (PMID 25052686, 2014). "In tumor cells, LOX activity promotes cell invasion and migration." (PMID 24265769, 2013). "The inhibition of the LOX enzymatic activity in the skin equivalent model induces basement membrane disruption and deregulation of filaggrin and K10 expression of the dermis, preparing a phenotype favorable to tumor development." (PMID 23425977, 2013). "Hypoxia may attenuate the expression of E-cadherin, via activation of the lysyl oxidase (LOX)-Snail pathway, to promote tumor invasion and metastasis." (PMID 24179495, 2013). "Interestingly, we showed that the tumor suppressor activity resides in the propeptide domain of LOX (LOX-PP), an N-terminal domain produced by proteolytic cleavage during the physiological processing of LOX." (PMID 23750284, 2013). "The expression of LOX was predominantly localized in the cytoplasm and nuclei of tumor cells." (PMID 23425977, 2013). "One of the tumor-secreted factors suggested to initiate the metastatic niche is LOX." (PMID 22509805, 2012). "Furthermore, hydrogen peroxide which is generated as a metabolic product of LOX activity, stimulates activity of the small GTPase Rac1 and thereby enhances the migratory/invasive behavior of tumor cells." (PMID 21914164, 2011). "This may be consistent with thetumour-promoting role of LOX but it raises the question whether the amount ofLOX produced by epithelial cells would be able tosignificantly affect tumour cells." (PMID 21479216, 2011). "However, LOX has also been reported to have animportant tumour promoting activity by favouring metastasis in breast, head, andneck cancers." (PMID 21479216, 2011). "However, paradoxical roles have been reported for LOX, functioning either as a tumor suppressor or metastasis promoter." (PMID 21139993, 2010). "HIF-1α activation correlates with metastasis and can promote metastasis through the regulation of key factors governing tumor cell metastatic potential, including E-cadherin, lysyl oxidase (LOX), connective tissue growth factor (CTGF), and plasminogen activator inhibitor-1 (PAI-1), CXCR4." (PMID 20953377, 2010). "Thus, a number of lines of research suggest a role for the FAK and Src kinases in regulation of vascular permeability during tumor cell extravasation, with LOX playing a regulatory role in this process." (PMID 19440335, 2009).
tumor (continued). "Our results suggest that LOX plays an important role in extravasation and/or tissue colonization by tumor cells, lending support to the idea that LOX inhibition might be useful in metastasis prevention." (PMID 19440335, 2009). "In a mouse orthotopic brain tumor model, inhibition of collagen crosslinking via LOX suppression reduces intratumoral collagen content, narrows tumor vessels, decreases vascular density, and lowers the expression of proangiogenic factors, collectively inhibiting tumor cell proliferation." (PMID 40721833, 2025). "Additionally, understanding the regulatory mechanisms of LOX expression could lead to novel therapeutic approaches, such as targeting upstream signaling pathways or combining LOX inhibition with immunotherapy to enhance anti - tumor immune responses." (PMID 40661776, 2025). "As such, the secretion of LOX not only by BC cells, but also potentially by stromal cells like adipocytes, could play a critical role in premetastatic niche formation and the likelihood of disseminated cancer cells to colonize secondary tumour sites." (PMID 38468823, 2024). "Besides the loss of LOX metallization, the accumulation of copper and ROS may also play a role in the inhibitory impact of ATP7A, suppressing tumor growth and metastasis." (PMID 39676279, 2024). "In addition, tumor-associated ECs produce non-conventional growth factors such as biglycan, lysyl oxidase (LOX) and pentraxin, sustaining angiogenesis processes." (PMID 38426109, 2024). "Therefore, targeting the interaction between ECM and TME cells in the tumor microenvironment is an important research direction for cancer treatment, including targeting MMPs and LOX to disrupt the fibrous network surrounding the tumor and promote immune cells infiltration." (PMID 38690275, 2024). "Similarly, LOX can activate epidermal growth factor (EGF) signaling to drive tumor metastasis." (PMID 39766266, 2024). "Additionally, as a coenzyme, a factor necessary for the cross-linking of collagen and elastin fibers, a copper ion can modify the extracellular matrix and create a suitable environment for tumor cell metastasis by enhancing the activities of lysyl oxidase (LOX) and lysine oxidase-like enzyme (LOXL)." (PMID 39539553, 2024). "Interestingly, LOX enzyme activity promotes tumor invasiveness and metastasis by modulating the extracellular matrix surrounding the tumor and actively simulating the formation of metastatic niches, while LOX-PP has tumor-growth inhibitory properties." (PMID 37298359, 2023). "Tumor cells and other tumor microenvironment (TME) cells, especially cancer-associated fibroblasts (CAF), produce collagen, which forms the majority of the tumor matrix and enhance the production of Lysyl oxidase (LOX), leading to collagen crosslinking, ECM rearrangement, and higher stiffness." (PMID 37468874, 2023). "We hypothesize that the overexpression of MMP14 might have certain advantages over the expression of secreted heparanase or the systemic application of lysyl oxidase inhibitors, as MMP14 is a membrane-anchored protein lowering the risk of structural changes outside of the tumor tissue." (PMID 37139603, 2023). "It is conceivable that Igfbp3 might interact with proteins that are sensitive to matrix stiffness, such as FAK and LOX, both of which serve as potentially crucial regulators of gene expression in cancer, influencing cell function and shaping the surrounding tumor microenvironment." (PMID 37653219, 2023). "Furthermore, the average general LOX gene DNA methylation level and tumor stage were analyzed." (PMID 36202905, 2022). "Combining our meta-analysis and bioinformatic exploration, we draw the following conclusions: (I) LOX expression was related to lymph node metastasis and tumor distant metastasis of GC patients but not correlated with gender, tumor differentiation, Lauren classification, and tumor depth of invasion." (PMID 36202905, 2022).